KRT20 (keratin 20)
Description:
Plays a significant role in maintaining keratin filament organization in intestinal epithelia. When phosphorylated, plays a role in the secretion of mucin in the small intestine (By similarity).
Synonyms: CK-20; K20; CK20; MGC35423; CD20; KRT21
Tractability: PROTAC: ubiquitination databases record sites on it.
Gene: Protein-coding gene on chromosome 17 (40,874,934 to 40,885,243, reverse strand). Ensembl gene ENSG00000171431.
Subcellular location: Cytoplasm
Subcellular location (Human Protein Atlas): Cytosol; Intermediate filaments
Pathways (Reactome):
Developmental Biology: Formation of the cornified envelope; Keratinization
Gene Ontology:
Molecular function: protein binding; structural constituent of cytoskeleton; structural constituent of skin epidermis; structural molecule activity
Biological process: intermediate filament organization; epithelial cell differentiation; morphogenesis of an epithelium; cellular response to starvation; regulation of protein secretion
Cellular component: cytoplasm; cytosol; cytoskeleton; intermediate filament; keratin filament
Genetic constraint (gnomAD): Loss-of-function variants: 35 observed, 36.86 expected, observed/expected ratio (o/e) 0.95, 90% interval 0.72 to 1.26. The upper end of that interval is the gene's LOEUF score, 1.26, which puts it in group 5 of 6, group 1 being the genes least tolerant of losing a copy. Missense variants: 443 observed, 458.9 expected, observed/expected ratio (o/e) 0.97, 90% interval 0.89 to 1.04. Synonymous variants: 171 observed, 176.97 expected, observed/expected ratio (o/e) 0.97, 90% interval 0.85 to 1.1.
Homologues: Orthologues: chimpanzee KRT20 (99% identical), macaque KRT20 (96% identical), rat Krt20 (82% identical), mouse Krt20 (79% identical), pig KRT20 (75% identical), dog KRT20 (71% identical), tropical clawed frog krt20 (48% identical). Paralogues in human: KRT14 (50% identical), KRT17 (48% identical), KRT16 (48% identical), KRT12 (48% identical), KRT13 (47% identical), KRT15 (47% identical), KRT24 (46% identical), KRT19 (45% identical), KRT27 (44% identical), KRT36 (44% identical), KRT10 (43% identical), KRT26 (42% identical), and 56 more.
Diseases named in the same sentence as KRT20 in open-access papers:
KRT20 is named in the same sentence as 112 diseases in open-access papers, as found by Europe PMC text mining. Sharing a sentence is not in itself a finding about the gene and the disease. The quoted sentences say what the papers report.
colorectal cancer (28 papers, 1998 to 2025). A primary or metastatic malignant neoplasm that affects the colon or rectum. "Keratin 7-negative and keratin 20-positive phenotypes were typical for colorectal carcinomas, although the loss of CDX-2 expression was noted in some colon rhabdoid carcinomas." (PMID 36732357, 2023). "KRT20 has historically served as a diagnostic marker for colorectal carcinoma, whereas high expression of ribosomal protein L32, glutaminase, and DEAD/H box polypeptides has been associated with various cancers and metastatic lesions." (PMID 19180177, 2009). "Indeed, the presence of neuropilin-2 in colorectal carcinoma cell lines was correlated with loss of epithelial markers such as cytokeratin-20 and E-cadherin and with acquisition of mesenchymal molecules such as vimentin." (PMID 21747928, 2011). "Colorectal cancers are typically characterized by a cytokeratin 7-negative/cytokeratin 20-positive (CK7−/CK20+) profile in 65.8% of cases, whereas primary breast cancers predominantly exhibit a CK7-positive/CK20-negative (CK7+/CK20-) pattern." (PMID 41458856, 2025). "Studies on pancreatic carcinoma, gastrointestinal cancers, colorectal carcinoma and miscellaneous tumors suggest that it is convenient to detect circulating tumor cells based on KRT20 RT-PCR assays." (PMID 36949761, 2023). "When neuropilin-2 was found in colorectal cancer cell lines, researchers discovered that epithelial markers like cytokeratin-20 and E-cadherin were lost and mesenchymal molecules like vimentin were acquired." (PMID 35052853, 2022). "LGR5-GFP human colorectal carcinoma (CRC) cells as well as KRT20 (keratin 20)-GFP CRC cells were generated and permitted the formation of CRC organoids (COOs) in Matrigel." (PMID 34298613, 2021). "We here report on a semi-quantitative real-time cytokeratin 20 RT-PCR-based assay, for detecting circulating tumor cells within a fraction of peripheral blood mononuclear cells in colorectal cancer patients." (PMID 29937995, 2018). "Cytokeratin 20 is expressed in most colorectal carcinomas and less frequently in upper gastrointestinal tract carcinomas." (PMID 23119210, 2012). "A highly sensitive system was previously developed by us to detect the presence of colorectal carcinoma cells in blood in the form of cytokeratin 20 (CK20) mRNA." (PMID 9579841, 1998). "In addition, by measuring KRT20 mRNA expression in lymph nodes is essential for exact tumor staging and for postoperative adjuvant treatment of colorectal cancer patients." (PMID 36949761, 2023). "Interestingly, cytokeratin 20 expression levels were down-regulated in colorectal cancer tissues compared to normal tissues, in contrast to ERBB3 in our studies, which suggests a more complex role for ERBB3." (PMID 26367378, 2015). "Moreover, according to HPA results, keratin 20 is enriched in colorectal cancer." (PMID 36949761, 2023). "Finally, we obtained evidence that both PHGR1 mRNA and protein may be promising biomarkers for the detection of metastases in colorectal cancer, as they have superior characteristics compared to the established metastasis marker KRT20." (PMID 29415677, 2018). "KRT19, KRT20, and VDR, which are markers of colonic enterocytes, were increased in reverted colorectal cancer cells." (PMID 39661721, 2025). "In this experiment, we used cytokeratin 20 (CK20) as a biomarker of colorectal cancer cells, as well as antibodies against cleaved caspase-3 or cleaved PARP-1." (PMID 35267627, 2022). "A similar pattern of expression has been observed in colorectal cancers using EPHB2 and cytokeratin 20 as a differentiation marker." (PMID 26367378, 2015). "The right ovarian tumor proved to be moderately differentiated adenocarcinoma that was positive for cytokeratin 20 and negative for cytokeratin 7 staining, indicating metastasis from the colorectal cancer." (PMID 30094696, 2018).
colorectal cancer (continued). "Cytokeratin 20 is not expressed in breast cancers but is found in pancreatic, gastric, and colorectal cancers, which aided diagnosis of adenocarcinoma of the colon in this case." (PMID 23984147, 2013). "Co-localization of cytokeratin 20 and oxMIF was detected by immunofluorescence microscopy indicating that these oxMIF positive vessel like structures originated from colorectal cancer cells and were not part of the tumor stroma originating from adjacent liver tissue." (PMID 27636991, 2016).
colon carcinoma (23 papers, 2008 to 2025). "In the group with induced colon cancer that was treated with MSCs, a moderate positive reaction to anti-cytokeratin 20 in the glandular cells of the mucosal layer was observed." (PMID 33604610, 2021). "In contrast, the colon sections from the group with induced colon cancer had intense staining of the anti-cytokeratin 20 body." (PMID 33604610, 2021). "On average, PHGR1 mRNA levels were 3.4 x 105 times higher in colon tumors than normal lymph nodes, whereas KRT20 mRNA levels were 1.3 × 105 times higher (P = 0.02)." (PMID 29415677, 2018). "The mean PHGR1 and KRT20 mRNA levels in examined colon cancers were 620- and 90-times higher than the mean level in the other tumor types tested (P < 0.001), respectively, indicating that PHGR1 is also more colon cancer-specific than KRT20." (PMID 29415677, 2018). "In colon cancer the standard for IHC is to detect the presence of aberrant cytokeratin 20 staining in lymph nodes, while in renal cancer cytokeratin 18 is used to demonstrate metastasis." (PMID 30290760, 2018). "Apart from carcinogenesis, adenocarcinoma at the anastomotic site is commonly believed to be of colonic origin and known to be positive for cytokeratin 20, a marker of colon cancer." (PMID 26649222, 2015). "Moreover, another study revealed that colon cancer tissue is structured similarly to the normal colon epithelium with LGR5+ stem cells that give rise to KRT20+/LGR5− differentiated cells." (PMID 39358322, 2024). "Moreover, HM of colon, colon cancer tissues and cell cultures expressed cytokeratin 18, whereas only healthy and cancer mucosa expressed cytokeratin 20, when analyzed by RT-PCR." (PMID 25738332, 2015). "While right-sided tumors display elevated gene expression levels of cell cycle control and Wnt signaling genes, left-sided colon cancers show reduced expression of tumor suppressor genes and cytokeratin 20 and elevated expression of COX-1 and genes that promote stromal expansion." (PMID 23049919, 2012). "In addition, cytokeratin 20 was expressed severely in colonic tissues of AOM induced colon cancer." (PMID 32458646, 2020). "To compare PHGR1 and KRT20 in this context, we measured PHGR1 and KRT20 mRNA levels in tumor biopsies from 209 patients with operable colon cancer and normal mucosa biopsies from 76 of the 209 patients." (PMID 29415677, 2018). "A subset of colon cancers showed crypt-like compartments with high WNT activity and nuclear β-Catenin at the leading tumor edge, adjacent proliferation, and enhanced Cytokeratin 20 expression in most differentiated tumor epithelia of the tumor center." (PMID 25111606, 2014). "It stained positive for cytokeratin 20, CDX2, and CEA, as colonic cancers do, but was also immunoreactive for cytokeratin 7 and p16, which are characteristic for the female genital tract neoplasms." (PMID 24307962, 2013). "The equivalence of RPL32 and KRT20 as well as the downstream relation of TFDP1 and DHX32 to these two genes is a first step toward refining the architecture of the colon cancer invasiveness network." (PMID 19180177, 2009). "In colon cancer, CD133+ cells were shown to be devoid of the intestinal epithelial differentiation marker cytokeratin 20 (CK20), whereas they keep positivity for the epithelial adhesion molecule EpCAM." (PMID 18781171, 2008). "Primary colon cancer is usually cytokeratin-7 negative and cytokeratin-20 positive, whereas endometrial cancers are usually cytokeratin-7 positive and cytokeratin-20 negative, and urothelial cancers are often positive for GATA-3." (PMID 40678160, 2025). "With the immunophenotyping of CSLC, the anti-CD133 antibody was found to be effective for isolating a population of colon cancer cells that retained the properties of stem cells (CSLC), while anti-cytokeratin 20 (CK20) and anti-Mucin-2 (MUC2) were specific epithelium colonic differenziation markers." (PMID 32927614, 2020).
colon carcinoma (continued). "Interestingly, a previous report suggests that in established human colon carcinomas, LGR5 expression remains basal and is exclusive from KRT20 expression." (PMID 25728748, 2015). "Interestingly, all adenocarcinomas including anastomotic site tumors were positive for cytokeratin 7 but negative for cytokeratin 20 and β-catenin nuclear accumulation, which is uncommon for colon cancers." (PMID 26649222, 2015). "Also, we observed that EPA induced down-regulation of CD133 expression and up-regulation of colonic epithelium differentiation markers Cytokeratin 20 and Mucin 2, indicating that n-3 PUFA increased the differentiation status of both bulk of tumor and CSLCs in colon cancer." (PMID 23874993, 2013). "Immunohistochemically, tumor cells from the ovaries and the colon both showed positive expression of cytokeratin 20 (CK20) but no expression of cytokeratin 7 (CK7), confirming that the ovarian tumors were metastases from primary colon cancer." (PMID 27842595, 2016).
bladder cancer (17 papers, 2014 to 2023). "The expression of KRT14 is seen in the least of the differentiated tumors and its expression correlates to poor prognosis KRT14, whereas the expression of KRT20 is restricted to differentiated bladder cancers and its expression is associated with good prognosis." (PMID 32822399, 2020). "Among the candidate molecules associated with urothelial differentiation are KRT20, a well established luminal marker, and FGFR3, STAG2, and PIK3CA—three major bladder cancer genes commonly altered in luminal tumors." (PMID 32635360, 2020). "KRT5 or KRT20 mRNA is considered a characteristic feature for a basal or luminal lineage, respectively, in bladder cancer." (PMID 33003392, 2020). "Previous investigations have successfully detected survirin, cytokeratin 20, mucin 7, and Ki-67 mRNAs in the urine of patients with bladder cancer and various urinary tract infections, highlighting the cells of the urogenital tract as major contributors of urinary RNAs12." (PMID 37925575, 2023). "Furthermore, luminal bladder cancer variants (micropapillary, plasmacytoid, nested) exhibited significantly lower levels of KRT5 and significantly higher levels of KRT20 expression than conventional UBC or basal variants (sarcomatoid, squamous)." (PMID 30380731, 2018). "Here, we have used RT-qPCR-based quantitation of predefined hallmark subtyping markers (KRT5/KRT20), with proven prognostic impact in muscle-invasive and non-muscle-invasive bladder cancer and which have been shown to have some predictive value in a finding cohort." (PMID 35887247, 2022). "In bladder cancer, KRT5/6 and KRT20 are used as combined markers in immunohistochemical analysis, which is helpful for the clinical evaluation of patient benefits from chemotherapy." (PMID 37671092, 2023). "These stages of differentiation also occur in bladder cancers with KRT14 expressed in the least differentiated bladder cancer and KRT20 expressed in the highly differentiated bladder cancers." (PMID 36293167, 2022). "We also detected some biological markers in the diagnosis of recurrent bladder cancer was dysregulated in UCB, including KRT20 (Cytokeratin 20), BIRC5 (Survivin), CDH1 (E-cadherin) and PSCA (Prostate Stem Cell Antigen-14)." (PMID 24622401, 2014).
Merkel cell carcinoma (15 papers, 2009 to 2025). "All tumors included in the present study exhibited the classic morphology of Merkel cell carcinoma and expressed diffusely chromogranin A, synaptophysin, and cytokeratin 20 (dot-like expression pattern)." (PMID 36298750, 2022). "Merkel cell carcinoma (MCC) is a highly aggressive skin cancer that is typically cytokeratin 20 positive on immunohistochemistry." (PMID 34063983, 2021). "The perinuclear localization pattern has been observed previously in normal Merkel cells and is also a feature of KRT20-positive cells in Merkel cell carcinoma." (PMID 30835771, 2019). "Most Merkel cell carcinoma are usually positive to cytokeratin 20, neuron-specific enolas, and neurofilament." (PMID 25253623, 2014). "In 1992, Dr. Moll and colleagues recognized that Cytokeratin 20 (CK20) expression was highly specific for Merkel cell carcinoma." (PMID 23691324, 2013). "Their differentiation is possible because antibodies to cytokeratin 20 and thyroid transcription factor 1 are specific to Merkel cell carcinoma and small cell lung carcinoma, respectively." (PMID 21729255, 2011). "Merkel cell carcinoma features cytokeratin 20 with a characteristic perinuclear dot pattern." (PMID 40084340, 2025). "Interestingly, the HCB-541 cell line had positive staining for cytokeratin 20, which is commonly used for the diagnosis of Merkel cell carcinoma and metastatic salivary gland tumors." (PMID 38565739, 2024). "KRT20 is expressed in epithelium of the gastrointestinal system and bladder, and in tumors of these tissues, but in skin its expression is limited to Merkel cells and Merkel cell carcinoma." (PMID 30835771, 2019). "Merkel cell carcinoma (MCC) is an uncommon and aggressive neuroendocrine skin tumor thought to originate from the Merkel cells of the basal layer of the epidermis given its shared cytoplasmic dense-core neuroendocrine granules and keratin filaments (cytokeratin-20) expression characteristics." (PMID 24840048, 2014). "In our case, cytokeratin 20 was negative, ruling out Merkel-cell carcinoma." (PMID 19178730, 2009).
breast carcinoma (13 papers, 2008 to 2024). "Among them, CCNE1 and KRT20 were of high expression in BRCA1/2-mutant breast cancer, and ALB and MYOM2 were of low expression." (PMID 31998560, 2020). "In contrast, luminal cancers express breast cancer differentiation markers (KRT20, CD24, ERBB2, and GATA3) and uroplakins which are markers of terminal urothelial differentiation." (PMID 28102366, 2017). "RARA, KRT19 and KRT20 amplification could be related to a more invasive breast cancer profile." (PMID 21288332, 2011). "In contrast, cytokeratin 20 is usually negative in breast carcinoma while gastric cancer cells display a focal and heterogeneous reaction." (PMID 25400965, 2014). "Breast cancer is typically cytokeratin 7-positive and cytokeratin 20-negative." (PMID 34410532, 2021). "The MD Anderson Cancer Center (MDACC) subtypes resembled those identified for breast cancer and showed typical mRNA expression profiles of basal and luminal markers, with keratin 5 (KRT5) expression being highly upregulated in basal and keratin 20 (KRT20) being upregulated in luminal tumors." (PMID 30380731, 2018). "Immunohistochemistry confirmed positive for cytokeratin 7(CK7), GATA-3 and GCDFP15, as well as negative staining of cytokeratin 20 (CK20), suggesting breast cancer metastasis." (PMID 38500767, 2024). "While markers usually positive in gastric adenocarcinoma such as cytokeratin 20, CDX2, MUC5AC, and Hep Par 1 were negative, those supporting breast carcinoma (estrogen and progesterone receptors, cytokeratin 7, and GATA3) decorated the cancer cells." (PMID 25400965, 2014).
urothelial carcinoma (9 papers, 2013 to 2025). A malignant neoplasm derived from the transitional epithelium of the urinary tract (urinary bladder, ureter, urethra, or renal pelvis). "High KRT20-expressing tumors as well as KRT20+/KRT− tumors were significantly enriched with aggressive urothelial carcinoma variants (micropapillary, plasmacytoid, nested)." (PMID 30380731, 2018). "Pathology revealed urothelial carcinoma with T2 disease at the lower ureter, plus spreading cytokeratin 7+ and cytokeratin 20+ pagetoid cells clustered within the epidermis indicative of secondary Paget's disease." (PMID 40336751, 2025). "Analogously, Cytokeratin 20 mRNA, a marker of differentiated urothelial cells expressed in many urothelial carcinomas, is increased in urinary sediments of UC patients." (PMID 28430799, 2017). "Basal cell markers like basal cytokeratins and CD44 are detected in the basal type urothelial carcinoma and markers of the luminal umbrella cells like cytokeratin 20 or uroplakin are found in the luminal type of urothelial carcinoma." (PMID 26316886, 2015). "Cytokeratin 20 belongs to cytoskeleton associated with intermediate filaments, cytokeratin 20 is specifically expressed in superficial and in some intermediate cells of normal urothelium but its expression beyond these limits may suggest progression to urothelial carcinoma." (PMID 25089155, 2014). "Urothelial carcinoma cells were positive for cytokeratin 20 (CK20), GATA3, p63, and CKHMW but negative for PSA." (PMID 35701835, 2022).